MYBL1 (MYB proto-oncogene like 1)
Diseases named in the same sentence as MYBL1 in open-access papers (continued):
Sharing a sentence is not in itself a finding about the gene and the disease.
glioma (28 papers, 2017 to 2025). A benign or malignant brain and spinal cord tumor that arises from glial cells (astrocytes, oligodendrocytes, ependymal cells). "For example, adult gliomas are often driven by IDH1 or IDH2 mutations, while subsets of low-grade pediatric gliomas are driven by rearrangements in the transcription factor-encoding proto-oncogenes MYB or MYB like 1 (MYBL1)." (PMID 38353122, 2024). "In conclusion, our study elucidates the diverse set of rearrangements that occur in the MYB and MYBL1 genes in MYB(L1)-altered glial neoplasms." (PMID 39422766, 2024). "MYB/MYBL1 altered diffuse glioma and angiocentric glioma show overlapping microscopic morphology and are characterized by MYB gene involvement." (PMID 39440342, 2024). "The results from a recent report on 33 MYB/MYBL1-altered glioma cases show that a substantial proportion of the cases (at least 13/33) exhibited a rearrangement of the MYB or MYBL1 gene in the absence of a recognizable fusion partner." (PMID 39422766, 2024). "Diffuse gliomas with MYB/MYBL1 rearrangement were mainly presented in children, and most of the patients had epileptic seizures together with neurological symptoms such as movement disorders, behavioral or memory changes." (PMID 38315329, 2024). "Research showed different molecular markers in tumors between children and adults, with pediatric low-grade gliomas predominantly exhibiting alterations in the BRAF, FGFR, and MYB/MYBL1 genes, while IDH1/2 mutations were less common." (PMID 38137148, 2023). "In the present study, we used multiple newly implemented techniques to investigate some of the genetic alterations in IDH1, IDH2, CDKN2A, MYB and MYBL1 in pediatric low-grade gliomas." (PMID 35574540, 2022). "All four MYBL1 tumours shared the same histological pattern as described in isomorphic glioma, with regular cells scattered in a fine bubbly neuropil." (PMID 35836307, 2022). "We found MYB- translocations with exon 2 or 3 of PCDHGA1 5/10 and 4/10 grade II gliomas respectively, and MYBL1 rearrangements in 6/9 of the samples examined." (PMID 35574540, 2022). "We thereby concluded with the integrated diagnosis of an intraventricular low-grade glioma with MYBL1 fusion." (PMID 33803647, 2021). "Multiple researches revealed that MYBL1 contributed to the occurrence and development of cancer, such as hepatocellular carcinoma, glioma, and adenoid cystic carcinoma." (PMID 34691188, 2021). "The newly established molecular subgroup comprises four distinct entities: 1) Diffuse astrocytoma, MYB or MYBL1-altered; 2) Angiocentric glioma; 3) Polymorphous low-grade neuroepithelial tumor of the young; and 4) Diffuse low-grade glioma, MAPK pathway-altered." (PMID 40861626, 2025). "Furthermore, MYBL1 has also been researched in other malignant tumors—its high expression was noted in breast tumors, salivary gland tumors, and pediatric glioma." (PMID 39408891, 2024). "There are few studies on the radiologic characteristics of MYB/MYBL1-altered gliomas." (PMID 38137148, 2023). "In glioma patients with MYB and MYBL1 mutations, the clinical course is generally indolent." (PMID 34638714, 2021). "cMYC inhibitor may hold promise for the management of tumors caused by MYB and MYBL1 translocations, Downstream MEK inhibitors are already in phase 2 in clinical trials for children with BRAF fused gliomas and phase 1 studies with FGFR1 inhibitors have started recently." (PMID 35574540, 2022). "No MYB(L1) fusion or rearrangement was detected in Case 9 by 3 different fusion callers including Arriba, although this case had been classified to the “Diffuse glioma, MYB- or MYBL1-altered” family with maximum confidence scores." (PMID 39422766, 2024). "Study cases included those which matched to the “Diffuse glioma, MYB- or MYBL1-altered” family by the CNS methylation classifier." (PMID 39422766, 2024).
glioma (continued). "This is particularly important to recognize in the AYA population, where gliomas with alterations in the MAPK pathway or MYB and MYBL1 have distinctly different prognoses from other glioma subtypes and offer possibilities for targeted therapy." (PMID 36249063, 2022). "In the IDH-wildtype glioma group (i.e., glioblastoma, low-grade glioma MYB/MYBL1 and (anaplastic) pleomorphic xanthoastrocytoma), MGMT promotor was methylated in 29% (5/17) and unmethylated in 71% (12/17) of the cases." (PMID 33941250, 2021). "The IDH-wildtype astrocytic glioma classified as low-grade glioma MYB/MYBL1 by methylation profiling, was negative for IDH1/IDH2 and BRAF mutations by sequencing analysis and was 1p/19q non-codeleted." (PMID 33941250, 2021). "MYBL1 belongs to the MYB family and is involved in adenoid cystic carcinoma and pediatric glioma." (PMID 29237456, 2017). "However, gliomas typically do not express histiocytic markers and exhibit other molecular characteristics, including IDH mutations, ATRX alterations, 1p/19q co-deletions, EGFR amplification, TERT promoter mutations, H3 mutations, MYB/MYBL1 gene structural mutations, and FGFR1 mutations, etc." (PMID 40231251, 2025). "Diffuse low-grade gliomas that are MAPK pathway-altered, or MYB- or MYBL1-altered, generally exhibit non-specific features characteristic of low-grade tumors." (PMID 38157879, 2023).
adenoid cystic carcinoma (20 papers, 2016 to 2025). A malignant tumor arising from the epithelial cells. "Previous reports implicated MYBL1 in adenoid cystic carcinoma and cutaneous adenocystic carcinoma." (PMID 33511207, 2021). "In the last decade, advances in molecular techniques have demonstrated recurrent genetic alterations in some salivary gland tumors, including the fusion of genes such as ETV6 in secretory carcinoma, MYB and MYBL1 in adenoid cystic carcinoma, and MAML2 in MEC." (PMID 39958930, 2025). "Around 80–90% of adenoid cystic carcinomas (AdCC) reveal MYB or MYBL1 activation by gene fusion, leading to overexpression of MYB-NFIB or MYBL1-NFIB fusion protein, respectively." (PMID 33237469, 2021). "MYBL1 and MYC genes are linked via the pathway associated with adenoid cystic carcinoma." (PMID 38473786, 2024). "These include fusions of the ETV6 gene in secretory carcinoma (SC), MYB/MYBL1::NFIB in adenoid cystic carcinoma (AdCC), CRTC1/CRTC3::MAML2 in mucoepidermoid carcinoma (MEC), and EWSR1::ATF1 in hyalinizing clear cell carcinoma as the most frequent and best characterized gene fusions." (PMID 38217715, 2024). "In fact, demonstrating a rearrangement of MYB, MYBL1, PLAG1, HMGA2, NTRK3, and a BRAF mutation in the appropriate morphological context is diagnostic of adenoid cystic carcinoma, cutaneous mixed tumor, secretory carcinoma, syringocystadenoma papilliferum, and tubular adenoma." (PMID 35158743, 2022). "Moreover, MYBL1 is highly expressed in adenoid cystic carcinoma and is often accompanied by genomic rearrangements." (PMID 34222474, 2021). "MYBL1 is a driver of adenoid cystic carcinoma when related to MYB." (PMID 29697361, 2018). "MYB-NFIB and MYBL1-NFIB gene fusions frequently occur in adenoid cystic carcinoma." (PMID 27083054, 2016). "For adenoid cystic carcinoma, multiple retrospective institutional series comprising aggregate numbers exceeding 200 cases, combined with well-characterized MYB/MYBL1 rearrangements and long-term outcome data, provide a robust evidence base." (PMID 41301002, 2025). "Co-expression of MYBL1 and MYC are detected in pharynx cancers, adenoid cystic carcinoma and breast, ovarian and lung cancers." (PMID 38473786, 2024). "Fusions among specific genes, namely myeloblastosis (MYB), MYB proto-oncogene like 1 (MYBL1), and nuclear factor I B (NFIB), have been related to adenoid cystic carcinoma." (PMID 37970205, 2023). "As adenoid-cystic carcinomas can feature genetic alterations in the MYB and MYBL1 genes, in addition to typical perineural invasion, further molecular pathological analyses of the tissue were performed." (PMID 32443830, 2020). "Myeloblastosis viral oncogene homolog-like 1 (MYBL1) belongs to the proto-oncogene family, and this MYB gene has been reported as an oncogene of adenoid cystic carcinoma." (PMID 31505835, 2019). "Finally, adenoid cystic carcinoma, a biphasic cell tumour with frequent rearrangement of the MYB or MYBL1 gene, is an important differential diagnosis of MSA." (PMID 38982505, 2024). "Due to the absence of nuclear pleomorphism, no increased mitotic rate, no perineural invasion and no fusion transcripts of the MYB or MYBL1 gene loci, an adenoid cystic carcinoma could be excluded." (PMID 32443830, 2020). "Finally, the existence of a ceruminous pleomorphic adenoma was assumed due to a lack of nuclear pleomorphism, no increased mitotic rate, no perineural invasion and no fusion transcripts of the MYB or MYBL1 gene loci for an adenoid cystic carcinoma." (PMID 32443830, 2020).
astrocytoma (11 papers, 2021 to 2025). "CNS_066, initially diagnosed as ganglioglioma, was reclassified as an astrocytoma with MYB or MYBL1 alterations." (PMID 41033792, 2025). "Astrocytomas that harbor recurrent genomic alterations in MYB or MYBL1 are a group of Pediatric-type diffuse low-grade gliomas that were newly recognized in the 2021 WHO Classification of Tumors of the Central Nervous System." (PMID 39422766, 2024). "Most patients with diffuse MYB/MYBL1-altered astrocytoma have a history of epileptic seizures since childhood." (PMID 37920791, 2023). "Most patients with diffuse MYB/MYBL1-altered astrocytoma had epileptic seizures since childhood and symptoms such as movement disorders, behavioral or mnestic changes occur with both encephalopathy and glioneuronal tumors." (PMID 35727368, 2022). "Not only did RNA-seq detect common fusions such as BRAF-KIAA1549 in 4 pilocytic astrocytomas, but it also detected rarer fusions including 2 cases with NTRK fusions, and one with a clear MYBL1 driver in an infiltrating astrocytoma." (PMID 35475276, 2022). "In contrast to the MYB/MYBL1-altered astrocytoma presented here, these tumors are usually not located in the cerebellum and do not contain dysmorphic neurons." (PMID 35727368, 2022).
breast carcinoma (11 papers, 2013 to 2024). "Our laboratory initially identified MYBL1 gene overexpression in a subset of TNBC cell lines following meta-analyses of breast cancers processed using DNA microarrays deposited at Gene Expression Omnibus (GEO)." (PMID 38473786, 2024). "Substantial amounts of data document the association of c-MYB and MYBL2 in a variety of cancers, including breast cancers, compared to fewer studies describing the involvement of the MYBL1 gene in cancer processes." (PMID 38473786, 2024). "For the most part, data presented in this study are consistent with previous observations showing over-expression and amplification of MYC in breast cancers, with a notable correlation between MYBL1 and MYC amplification alterations in the TCGA 1015 patient sample TNBC dataset." (PMID 38473786, 2024). "Although the contribution of MYBL1, encoding for the homolog of the oncogene MYB, to the development of breast cancer is unknown, in a previous report it was strongly induced by E2 but only marginally by phytoestrogens such as curcumin." (PMID 23305139, 2013). "MYBL1 belongs to a group of genes that encode the MYB proto-oncogene protein; MYB has been shown to be highly expressed in ER+ breast tumors and tumor cell lines and is essential for the proliferation of ER+ breast cancer cells." (PMID 24564956, 2013). "Among cell cycle process-related genes, we found that DDIAS and MYBL1 were particularly overexpressed in invasive ductal breast carcinoma (IDC) or invasive lobular breast carcinoma (ILC) samples than normal breast tissues in TCGA breast cancer dataset retrieved from the OncomineTM Platform." (PMID 35681031, 2022). "Further study is needed to investigate the role of MYBL1 and RET in estrogen induced breast cancer development." (PMID 23305139, 2013). "In breast carcinoma tissue with overexpression of the HER2 receptor, a high level of miRNA-221 was also found, and it was shown that it leads to reduced expression of MYB and MYBL1." (PMID 39408891, 2024). "Similar to MYB, both MYBL1 and MYBL2 are upregulated by ESR1 signaling in breast cancer cells." (PMID 30833639, 2019). "Finally, MYB, MYBL1 and MYBL2 were reported to be upregulated by ESR1 signaling in breast cancer cells." (PMID 30833639, 2019). "Finally, using miR mimic overexpression and TIMP2 siRNA knockdown, we show that a miR-221/222, miR-503 → MYB, MYBL1 → TIMP2 axis stimulates migration and invasion of MCF-7 breast cancer cells." (PMID 30833639, 2019). "In conclusion, the present results suggest that PSPC1 would facilitates hormone-dependent breast cancer proliferation by exhibiting RNA processing of ESR1 and SCFD2, the latter further contributes to anti-apoptotic or proliferative responses by modulating the expression of DDIAS and MYBL1." (PMID 35681031, 2022). "The miR-221/222/503 – MYB/MYBL1 - TIMP2 – cell motility axis was recapitulated in both T47D cells (Luminal A subtype) and SKBr-3 cells (HER2-positive subtype), suggesting a the signaling axis is universal rather than cell line/breast cancer subtype specific." (PMID 30833639, 2019).
neuroepithelial tumor (7 papers, 2017 to 2025). "However, shared mutations of MYB/MYBL1 abnormalities can occur in other low-grade neuroepithelial tumors, including DA (26–41%), d-OT (8%), IDG (77%), MYBL1 (54%), MYB (23%), and DNET (in one case)." (PMID 36699536, 2022).
breast tumors (4 papers, 2013 to 2024). "Moreover, we identified DDIAS and MYBL1 as SCFD2 downstream target genes using microarray analysis, and finally showed that SCFD2 silencing suppressed tamoxifen-resistant breast tumor growth in vivo." (PMID 35681031, 2022).
colon cancer (4 papers, 2021 to 2025). "We found that inhibition of HDAC4, but not HDAC10, down-regulates the mRNA level of YAP and MybL1 in prostate and colon cancer cells." (PMID 41281751, 2025). "In colon cancer cells, O-GlcNAc epigenetically regulates the expression of MYBL1, a protein that is highly expressed in cancer to promote malignant development, which in turn regulates the population of cancer stem-like cells and tumor growth." (PMID 37838167, 2023). "Cancer stem-like cell population in colon cancer is negatively regulated by MYBL1, which is a target for O-GlcNAc regulation." (PMID 37838167, 2023). "Interestingly, in our study we found that MYBL1 was not only overexpression in HCC but also in other gastrointestinal malignancy (pancreatic cancer, esophageal carcinoma, stomach adenocarcinoma, colon cancer), and upregulation of MYBL1 induces angiogenesis promotes HCC cells metastasis." (PMID 35987690, 2022). "Importantly, we confirmed the correlation between MYBL1 and ANGPT2 expression in a large cohort of clinical HCC samples and several published datasets in pancreatic cancer, esophageal carcinoma, stomach adenocarcinoma, and colon cancer." (PMID 35987690, 2022).
hepatocellular carcinoma (4 papers, 2021 to 2025). A malignant tumor that arises from hepatocytes. "For example, MYBL1 promoted the hepatocellular carcinoma growth and metastasis via upregulation of TWIST1." (PMID 34691188, 2021). "Studies have confirmed that in Hepatocellular Carcinoma (HCC), AMYB proto-oncogene-like 1(MYBL1) binds to the ANGPT2 promoter and upregulates ANGPT2 mRNA expression." (PMID 40061897, 2025).
leukemia (4 papers, 2017 to 2022). A malignant (clonal) hematologic disorder, involving hematopoietic stem cells and characterized by the presence of primitive or atypical myeloid or lymphoid cells in the bone marrow and the blood. "Recurrent chromosomal translocations involving the genes MYB and MYBL1 produce NRD truncated versions of the respective proteins c-Myb and A-Myb that are sufficient to induce leukemias in mice." (PMID 35926712, 2022).
low grade glioma (4 papers, 2017 to 2025). A grade I or grade II glioma arising from the central nervous system. "In addition, 2% (2/131) of the cases were classified as other tumor types than diffuse glioma, i.e., low-grade glioma MYB/MYBL1 and (anaplastic) pleomorphic xanthoastrocytoma." (PMID 33941250, 2021).
salivary gland tumors (4 papers, 2024 to 2025). "Related to other cancers, MYBL1/VCPIP1 gene fusions were detected in salivary gland tumors supporting a documented relationship between the two genes." (PMID 38473786, 2024). "Other than the fact that MYBL1 and VCPIP1 genes are associated with cell cycle signaling events and a MYBL1-VCPIP1 fusion product has been observed in salivary gland tumors, no experimental data support a relationship between the two genes." (PMID 39796135, 2024). "In contrast, other than the identification of a MYBL1-VCPIP1 gene fusion event in salivary gland tumors, a possible relationship between MYBL1 and VCPIP1 genes has not been established." (PMID 39796135, 2024).
Burkitt lymphoma (3 papers, 2012 to 2017). A rare form of malignant mature B-cell non-Hodgkin lymphoma. "MYBL1 is highly expressed in Burkitt's lymphoma cells, some chronic lymphocytic leukemia, and a small subset of human neoplastic B-cells and stimulates the proliferation and differentiation as a member of the Myb oncogene family of transcription factors." (PMID 28423735, 2017). "MYBL1 could be involved in DLBCL pathogenesis in addition to its role in Burkitt lymphoma or chronic lymphoid leukemia (CLL)." (PMID 23482333, 2012).
clear cell renal cell carcinoma (3 papers, 2022 to 2024). "Studies of clear cell renal carcinoma show that MYBL1 expression correlations with the immune scores, increasing Tregs, M2 macrophages, neutrophils, B cells, monocytes, and CD8+ T cells." (PMID 39796135, 2024). "The MYBL1 gene is also over-expressed in clear cell renal carcinoma and considered an immunotherapeutic biomarker for these cancers." (PMID 39796135, 2024). "The authors suggest that MYBL1 can ultimately remodel the tumor micro-environment, but it is unclear how MYBL1 might enhance the cellular malignant behaviors of clear cell renal carcinomas." (PMID 39796135, 2024). "The over-expression of MYBL1 also correlates with the overexpression of the key immune checkpoint genes PD-1, CTLA4, PD-L1, and PD-L2 in clear cell renal cell carcinoma patients." (PMID 39796135, 2024).
diffuse midline glioma (3 papers, 2023 to 2025). A diffuse glioma that arises from the midline structures of the central nervous system. "Two tumors each (3.8%) belonged to the diffuse midline glioma, H3 K27-altered, the diffuse LGG, MYB/MYBL1-altered, and the adult-type glioblastoma, IDH-wt, tumor (sub-)types, respectively." (PMID 38717379, 2024).
malignant lymphoma (3 papers, 2015 to 2017). "MYBL1 located in the chromosome region 8q22 is involved in recurrent translocations in malignant lymphoma." (PMID 26869285, 2016). "MYBL1, which is located in chromosome region 8q22, could be involved in recurrent translocations in malignant lymphoma." (PMID 28423735, 2017). "Interestingly, MYBL1 is located in the chromosome region 8q22, which is involved in recurrent translocations in malignant lymphoma; therefore, MYBL1 could be a candidate for involvement in such translocations." (PMID 25940947, 2015).
oligodendroglioma (3 papers, 2017 to 2025). A well-differentiated (WHO grade II), diffusely infiltrating neuroglial tumor, typically located in the cerebral hemispheres. "Rearrangements and copy number abnormality in MYB or MYBL1 resulting in upregulated MYB or MYBL1 are found in more infiltrative pLGGs including grade 2 DAs, angiocentric gliomas and oligodendroglioma." (PMID 38318325, 2023).